FAM20A (FAM20A golgi associated secretory pathway pseudokinase)
Diseases named in the same sentence as FAM20A in open-access papers (continued):
Sharing a sentence is not in itself a finding about the gene and the disease.
Sepsis (1 paper, 2023). Sepsis is defined as life-threatening organ dysfunction caused by a dysregulated host response to infection. "Classification of data split into three separate groups: Controls, SIRS and Sepsis achieved an OOB estimate of error rate of 17.99% across all days, revealing three biomarkers of most importance by feature selection i.e., FAM20A, OLAH and DAAM2." (PMID 38332914, 2023). "Nineteen high-performance, differentially expressed mRNA biomarkers were identified between control and combined SIRS/Sepsis groups (FC>20.0, p<0.05), termed ‘indicators of inflammation’ (I°I), including CD177, FAM20A and OLAH." (PMID 38332914, 2023). "CD177, ARG1, FAM20A, PCOLCE2, SLC51A, MMP9, were identified as most significantly upregulated in both SIRS and Sepsis on Day1, compared with healthy controls, with CD177 and ARG1 consistently higher for both SIRS and Sepsis at this and across all timepoints to discharge." (PMID 38332914, 2023). "Significant differences between S and DNS were observed between SIRS and ABDM but not PLMN sepsis for small signatures: FAM20A+OLAH, ADM+FAM20A+OLAH (p <0.05)." (PMID 38332914, 2023). "Top ranked hits included FAM20A, PPARG, ADM and ARG1, many of which are commonly expressed in both SIRS and sepsis disease groups relative to controls and are non-specific." (PMID 38332914, 2023).
ST Elevation Myocardial Infarction (1 paper, 2025). A myocardial infarction that produces elevation in the ST segments of the ECG. "FAM20A, a secreted pseudo kinase essential for biomineralization, regulates calcium-phosphate metabolism and is known to be upregulated in conditions such as ST-elevation myocardial infarction, also via the IL-6/JAK/STAT3 signaling." (PMID 40877937, 2025).
tooth disorder (1 paper, 2025). A disease involving the calcareous tooth. "Mutations in FAM20A are associated with various tooth disorders, named human amelogenesis imperfecta and gingival hyperplasia syndrome, and in some cases the renal calcification is also involved along with tooth disorders such as in enamel renal syndrome." (PMID 40422215, 2025).
cancer (4 papers, 2019 to 2024). A tumor composed of atypical neoplastic, often pleomorphic cells that invade other tissues. "Utilizing the TCGA, GTEx, and CGGA databases, we focused on the gene encoding Family with Sequence Similarity 20, Member A (FAM20A) across various cancers." (PMID 38983866, 2024). "Building on previous studies that link the prognosis of various cancers to different immune cell types, we examined the association between FAM20A expression and immune cells in LUSC patients." (PMID 38983866, 2024). "Neutrophils exert significant anti-tumor effects, and our findings suggest that reduced FAM20A expression in all LUSC stages may impair immune responses to cancer cells." (PMID 38983866, 2024). "According to the GTEx database, FAM20A is downregulated in various cancers." (PMID 38983866, 2024).
bacterial infection (2 papers, 2023 to 2025). "Density plots for the selected genes displayed separate, but overlapping expression patterns with ITGA7, ITGB4 and FAM20A exhibiting higher expression in subjects with bacterial infection and the interferon-related gene IFI27 exhibiting higher expression in subjects lacking a bacterial infection." (PMID 40060038, 2025).
infection (2 papers, 2023 to 2025). The state of being infected such as from the introduction of a foreign agent such as serum, vaccine, antigenic substance or organism. "Among them, eight DEGs (RF00100, NXPH2, SEC61G, GADD45G, TUBAL3, LIPE, CSRNP1, and FAM20A) were shared across different comparison groups after FX0910 infection." (PMID 37982609, 2023). "A hard-thresholded, mostly relaxed, LASSO-constrained logistic regression model was used to select a parsimonious gene set (ITGB4, ITGA7, IFI27, FAM20A) highly capable of discriminating any bacterial from nonbacterial infection (cross validated AUC = 0.90)." (PMID 40060038, 2025).
kidney disease (2 papers, 2015 to 2023). "Given the recessive inheritance pattern seen in all previous FAM20A mutation‐positive families and the potential for renal disease, further screening was carried out to look for a second pathogenic allele." (PMID 26740946, 2015).
tumor (2 papers, 2021 to 2024). "In summary, our study proposes an association between FAM20A and tumor immunity, positioning it as a potential immune therapy target in LUSC." (PMID 38983866, 2024). "A focal point of our findings was the expression pattern of FAM20A, a gene of interest due to its suggested role in tumor suppression." (PMID 38983866, 2024). "To delve deeper into FAM20A’s role in the tumor microenvironment, metabolism, and DNA repair, we examined its correlation with various oncogenes." (PMID 38983866, 2024). "Our research indicates a positive correlation between FAM20A and immune cells, implying its pivotal role in modulating the tumor immune microenvironment (TIME) in LUSC." (PMID 38983866, 2024). "This offers novel insights into enhancing anti-tumor immune responses through targeted modulation of FAM20A." (PMID 38983866, 2024). "We discovered that FAM20A expression inversely correlates with tumor purity in LUSC, and positively correlates with the presence of B cells, CD8+ T cells, CD4+ T cells, macrophages, neutrophils, and dendritic cells." (PMID 38983866, 2024). "Then, utilizing multiple public databases, we identified FAM20A as a potential tumor-suppressive gene at all LUSC stages." (PMID 38983866, 2024). "In LUSC, a lower percentage of TILs in conjunction with reduced FAM20A expression implies a potential role in tumor immune evasion." (PMID 38983866, 2024). "Collectively, our findings position FAM20A as a novel tumor suppressor in LUSC, potentially influencing tumor immune interactions and serving as a prognostic biomarker." (PMID 38983866, 2024). "Whereas, compared with the healthy controls, the transcription levels of FAM20A are greatly reduced in tumor cells." (PMID 38983866, 2024). "Initially, our analysis of the FAM family revealed that FAM20A potentially assumes a tumor-suppressive role in LUSC development, a hypothesis we subsequently confirmed with clinical samples." (PMID 38983866, 2024). "Its expression positively correlates with immune cells, suggesting that decreased FAM20A levels in LUSC patients may contribute to tumor cell immune evasion." (PMID 38983866, 2024). "Similarly, dendritic cells, known for their anti-tumor responses through antigen presentation and T cell activation, also showed a positive correlation with FAM20A, whether plasmacytoid or activated." (PMID 38983866, 2024). "In this study, utilizing the TCGA database, we explored FAM20A in LUSC and uncovered its tumor-suppressive function." (PMID 38983866, 2024). "Further validation of FAM20A and FAM20C expression in tumor samples was performed through mRNA level analysis using the TCGA database." (PMID 38983866, 2024). "Unexpectedly, despite identifying FAM20A as a tumor suppressor in LUSC, its expression did not correlate with patient prognosis." (PMID 38983866, 2024).
genetic disorder (1 paper, 2022). "Enamel Renal Syndrome (ERS) is a rare genetic disorder caused by biallelic mutations in Family with sequence similarity 20A (FAM20A) gene encoding the secretory pathway pseudokinase FAM20A." (PMID 36091358, 2022).
FAM20A also shares sentences with these, for which no sentence is quoted: Amelogenesis imperfecta type 1G (1 paper); congenital adrenal hyperplasia (1); COVID-19 (1); distal renal tubular acidosis (1); enamel hypoplasia (1); hepatocellular carcinoma (1); Hypercalciuria (1); hyperphosphatemia (1); Hypocalciuria (1); nephrolithiasis (1); periodontal disease (1); primary failure of tooth eruption (1); pulp stones (1); renal dysfunction (1); renal failure (1); tooth agenesis (1).